CD47 (CD47 molecule)
Diseases named in the same sentence as CD47 in open-access papers (continued):
Sharing a sentence is not in itself a finding about the gene and the disease.
cancer (continued). "CD47–SIRPα signaling is involved in the development of diseases including cancer, and since short SIRPα is expressed as widely as long SIRPα, we believe that these findings will provide important perspectives into the mechanisms of onset and the development of treatments for these diseases." (PMID 40763927, 2025). "Our in vitro studies demonstrated that 1B2–10 effectively disrupted the interaction between CD47 and SIRPα, thereby abrogating the “don’t eat me” signal and resulting in a significant enhancement of macrophage-mediated phagocytosis against CD47-expressing cancer cell lines." (PMID 41383500, 2025). "Future studies should systematically profile the palmitoyltransferase ‘landscape’ governing CD47 modification across cancer types, as combinatorial inhibition of multiple ZDHHCs may increase the efficacy of CD47-targeted therapies." (PMID 41163221, 2025). "Consequently, improving strategies focused on the CD47-SIRPα interaction is crucial for advancing cancer treatment." (PMID 41350707, 2025). "Notably, CD47 exhibited high expression in all cancers, consistent with its role in immune evasion by inhibiting macrophage-mediated phagocytosis." (PMID 40396172, 2025). "In cancer patients, CD47 was found to determine the prognostic significance of TAMs." (PMID 39994810, 2025). "Reducing the αCD47 concentration, while still showing efficient CAR-M-mediated phagocytosis of cancer cells, may reduce off-target effects when used in patients, given that almost all healthy cells express some level of CD47." (PMID 40082557, 2025). "Blocking the CD47–SIRPα axis is a promising immunotherapeutic strategy against cancer." (PMID 40402266, 2025). "Furthermore, both ouabain and digoxin enhanced the anti‐cancer effect of CD47 antibody in this study." (PMID 40985476, 2025). "Blocking the CD47-SIRPα axis was considered to be a promising option for cancer treatment." (PMID 40861801, 2025). "The blockade of CD47/SIRPα is an emerging target in cancer immunotherapy." (PMID 40356923, 2025). "On one hand, CD47 overexpression allows cancer cells to evade immune clearance by binding to SIRPα." (PMID 40016734, 2025). "Moreover, hNVs block the CD47-SIRPα interaction, enhancing macrophage-mediated cancer cell phagocytosis and boosting antitumor T-cell immunity." (PMID 40528159, 2025). "Since our anti-SIRPα antibodies are capable of blocking the SIRPα/CD47 interaction, we next sought to assess whether our antibodies can restore and enhance macrophage phagocytic activity against cancer cells." (PMID 40136470, 2025). "These bispecific antibodies could block the SIRPα-CD47 interaction and directly target cancer cells, potentially enhancing anti-cancer effects and mitigating resistance mechanisms." (PMID 40136470, 2025). "Moreover, a nanoassembly, PP-(hDOX&siCD47), formed by DOX-conjugated polyphosphoester and CD47-targeting siRNA, enhances cancer immunotherapy by blocking CD47 and triggering ICD." (PMID 39742149, 2025). "Additionally, molecules like microRNA miR-340 and the polypeptide PEP-20 have been found to target CD47, boosting macrophage phagocytosis of cancer cells." (PMID 41019045, 2025). "However, studies have shown that cancer- and virus-infected cells upregulate CD47 as an immune evasion mechanism." (PMID 40573933, 2025). "Indeed, anti-CD47 antibodies or SIRPα-Fc fusion proteins inhibit the “don’t eat me” signal by blocking the CD47- SIRPα axis and unmask the “eat me” (pro-phagocytic) signals expressed on cancer cells, thus promoting macrophage phagocytosis." (PMID 40369208, 2025). "This makes the CD47-SIRPα interaction a promising target for cancer immunotherapy." (PMID 40070841, 2025). "We postulated that the SIRPα-αMSLN LicMAb specifically blocks CD47 on MSLNpos cancer cells." (PMID 40402266, 2025).
cancer (continued). "Immunofluorescence analysis showed that overexpression of CD47 inhibited the co‐localization of cancer cells with macrophages compared to CD47/K16R mutant, suggesting that overexpression of CD47 inhibited phagocytosis, whereas the CD47/K16R mutant reversed this event." (PMID 39665172, 2025). "CD47 is overexpressed in various cancer cells and correlates with distant metastases." (PMID 41354057, 2025). "This mRNA-derived CD47 inhibitor effectively activated macrophages against cancer cells in vitro." (PMID 40652522, 2025). "The side effects caused by non-targeted cancer cells and the negative impact on the interaction between CD47 and other receptors have become major obstacles limiting the widespread application of first-type antibodies in the treatment of solid cancers." (PMID 40589735, 2025). "This enables CD47 to become an important biomarker for cancer treatment and prognosis." (PMID 40385528, 2025). "While normal cells also express CD47, many cancer types, including AML, overexpress this receptor." (PMID 40361435, 2025). "Although the absence of costimulatory signals prevents the direct activation of T cells, our study revealed that MHC-II+ cancer cells exhibit upregulated CD47 expression, which enhances their interaction with SIRPα on macrophages and transmits a "don't eat me" signal that inhibits phagocytosis." (PMID 41281745, 2025). "Anti‐CD24 treatment can still be effective in cancers that have been resistant to CD47 blockade." (PMID 41354057, 2025). "Many authors described how blocking the CD47/SIRP-α pathway might be a target therapy against various cancers." (PMID 40867316, 2025). "This may be due to increased expression of immune checkpoint inhibitors such as CD47 (cluster of differentiation 47, which inhibits phagocytosis and cytotoxicity of phagocytes on host and cancer cells) and matrix metalloproteinase 9 (MMP-9)." (PMID 41011327, 2025). "Of the three cancer cell lines examined, B16-F10 cells were most susceptible to NDV-GFP infection, as evidenced by the highest percentage of GFP-positive cells, and this directly correlated with CD47 expression." (PMID 41322194, 2025). "Through an analysis of data obtained from a screening model focused on the macrophage‐mediated killing effect, two cardiac glycosides (CGs), ouabain and digoxin, are shown to increase the capacity of macrophages to kill cancer cells after combination with CD47 antibody." (PMID 40985476, 2025). "The CD47-SIRPα axis remains a compelling and versatile target in cancer immunotherapy." (PMID 41179296, 2025). "Targeting CD47 has emerged as a promising therapeutic approach, particularly in cancer and CVDs." (PMID 41303525, 2025). "CD47 not only promotes immune evasion but also sustains the survival of cancer stem cells." (PMID 40396172, 2025). "CD47, recognized as a transmembrane protein, is highly expressed on both normal and cancer cells." (PMID 40487639, 2025). "Moreover, the hypomethylation activity of Aza increases the expression of calreticulin and CD47 on cancer cells, which increases both the pro-phagocytic and anti-phagocytic signals on the cells." (PMID 40361435, 2025). "CD47 is currently becoming a “hot” target for cancer immunotherapy." (PMID 40185975, 2025). "One of the top ligands induced by Mφs (i.e., expressed higher in CAFs in the Tri condition than CoCAF) was signal regulatory protein alpha (SIRPA), which is a well‐known ligand that mediates cancer immune evasion by activating the CD47 expression on cancer cells." (PMID 40056038, 2025). "A CD47 antibody called lemzoparimab has now shown favorable cancer efficacy in the clinic." (PMID 40979214, 2025). "Flow cytometry analysis showed that ATG9A KO did not alter the expression of key phagocytosis checkpoints (MHC-I, PD-L1, CD24, CD47) or the CAR target EphA2, suggesting ATG9A regulates cancer cell susceptibility to macrophage killing through a specific and independent mechanism." (PMID 40595560, 2025).
cancer (continued). "Activating EGFR mutations could transcriptionally increase CD47 expression via the activation of ERK/c‐Myc and AKT/NF‐κB signaling, which impairs macrophage phagocytosis and mediates innate immune evasion of cancer cells." (PMID 40859900, 2025). "Specifically, ouabain combined with CD47 antibody had the best phagocytosis index (1.46‐fold change compared with CD47 antibody alone), whereas digoxin had the best clearance effect (0.39‐fold change compared with CD47 antibody alone) on the remaining cancer cells." (PMID 40985476, 2025). "Moreover, NEAT1‐31 and anti‐CD47 promoted the elimination of cancer cells and prolonged the survival time of mice with BRCA and GBM." (PMID 40344649, 2025). "CD47, found on both healthy and malignant cells, regulates macrophage-mediated phagocytosis by sending a “don’t eat me” signal to the signal-regulatory protein alpha (SIRPα) receptor, being a popular target for clinical trials in cancer immunotherapy." (PMID 40361334, 2025). "Therefore, targeting an ICP of myeloid cells and the innate immune system, CD47, serves as a prospective strategy for cancer immunotherapy." (PMID 41233805, 2025). "This suggests that the CD47 ECD is a subpar target for cancer therapy." (PMID 41511354, 2025). "In addition, MYC upregulation by F. nucleatum positively stimulates PD-L1 and CD47 expression in cancer cells." (PMID 41011327, 2025). "When α CD47, a CD47 antibody, was loaded into Al-MOFs for cancer treatment, it could bind to CD47 on the surface of cancer cells, relieving CD47 signal-blocking and leading to immunity activation." (PMID 40006592, 2025). "Hu5F9-G4, a CD47 inhibitor, enhances the phagocytosis of cancer cells through macrophages." (PMID 39275127, 2024). "The coexpression of CD47 and PD-L1 on various human tumors, confirmed by multiplex fluorescent immunohistochemistry staining, supports the potential of 6MW3211 for clinical trials targeting PD-L1+ CD47+ cancers." (PMID 38475778, 2024). "Higher CD47 expression in some cancers correlates with decreased patient survival." (PMID 39201643, 2024). "CD47 has also been proven to be a potential target for cancer immunotherapy." (PMID 38532108, 2024). "However, CD47 mRNA expression in some cancers lacks correlation or correlates with improved survival." (PMID 39201643, 2024). "In response to this pro-phagocytic stimulus, cancer cells may upregulate CD47 as a protective mechanism to evade both phagocytosis and the immune system." (PMID 39767726, 2024). "Taken together, Tug1 could promote Cd47 expression by sponging miR‐340, and consequently inhibit the phagocytosis function of macrophages toward cancer cells, thus playing a critical role in the regulation of antitumor immune response." (PMID 38981064, 2024). "Our findings support our hypothesis that CD36 and CD47 can be used as prognostic biomarkers for multiple cancer indications." (PMID 39627379, 2024). "The CD47-SIRPα pathway is the most extensively researched checkpoint for phagocytosis in cancer." (PMID 38881902, 2024). "Despite the successful application of anti-CD47 and anti-SIRPα blocking antibodies in immunotherapy against cancer cells, the potential of engaging SIRPα to restrain excessive immune activation in the context of ILC2s and allergic lung inflammation remains unexplored." (PMID 39160226, 2024). "This revealed that differences in CD47 expression levels may be due to multiple factors in stem-like cells of nest-cancer cells." (PMID 38832992, 2024). "Consequently, cancer cells express both CD47 and pro-phagocytic signals, whereas healthy normal cells only express CD47." (PMID 39767726, 2024). "The capability of ALK to induce an adaptive immune response in ALK-driven cancers could be integrated with the restoration of the innate immune system by blocking CD47-mediated DEMs within the TME." (PMID 39767726, 2024).
cancer (continued). "Elevated expression of CD47 is observed in a wide range of cancer cells as a mechanism for evading the immune system, blocking the interaction between the CD47 and SIRPα is the most advanced and promising therapeutic approach currently investigated in multiple clinical trials." (PMID 38426113, 2024). "Because IFT57 showed stronger correlations than CD47 with poorer survival in several cancers, the assumption that the ‘don’t eat me’ function of CD47 accounts for such correlations may need to be reevaluated." (PMID 39201643, 2024). "CD47, as an antiphagocytic “don’t eat me” signal, is important for cancer treatment." (PMID 38383737, 2024). "Targeting CD47 to disrupt its interaction with SIRPα can enhance the immune system’s ability to destroy cancer cells and could be explored to prevent autoinflammatory diseases." (PMID 39039207, 2024). "Of note, our screen also identified putative drug-drug interactions that may negatively affect CD47-blocking therapies or other macrophage-directed therapies for cancer." (PMID 38483480, 2024). "However, the combination of any EGFR TKI with an anti-CD47 antibody dramatically eliminated cancer cells and prevented development of persister cells." (PMID 38483480, 2024). "The virus blocks the “don’t eat me” signal of CD47 in cancer cells." (PMID 38832992, 2024). "Moreover, the overexpressed SIRPα on gCMs enhanced the cancer immunotherapy by disrupting the CD47-SIRPα signaling pathway." (PMID 38699238, 2024). "Cancer cells use “don’t eat me” signals (DEMs), such as CD47, to resist TAMs-mediated phagocytosis." (PMID 39767726, 2024). "Moreover, it reduced the expression of CD47, promoting increased phagocytosis of cancer cells and more significant T-cell infiltration by inhibiting their apoptosis." (PMID 38891880, 2024). "Importantly, these results highlight the potential of implementing CD36/CD47 as dual markers to select patients for VT1021 treatment in a broad range of cancer indications." (PMID 39627379, 2024). "High levels of CD47 expression are prognostic indicators of poor outcomes for cancer patients." (PMID 39627379, 2024). "Next, we investigated whether blocking CD47 on cancer cell membranes using nanobodies could enhance their phagocytosis by macrophages." (PMID 38247566, 2024). "CD47 is overexpressed in various gynecological cancers such as ovarian and endometrial cancers, contributing to immune evasion by inhibiting macrophage phagocytosis of cancer cells." (PMID 38892394, 2024). "Moreover, immunofluorescence (IF) analysis of two cancer nodule sections obtained from patient 1 with BC indicated the presence of CD47 and CD24, which had a broad distribution within the cytoplasm and membrane of malignant cells." (PMID 38971872, 2024). "However, the combination of an ALK inhibitor with an anti-CD47 antibody yielded the greatest antitumor response, effectively eliminating all cancer cells from the culture." (PMID 38483480, 2024). "One example is the CD47 protein, which can be found overexpressed in many types of cancer and is related to the malfunctioning of macrophages and dendritic cells and is, therefore, an indicator of poor cancer survival." (PMID 38790954, 2024). "Magrolimab is a first-in-class investigational monoclonal antibody against CD47 and macrophage checkpoint inhibitor, which interferes with the recognition of CD47 by the SIRPα receptor on macrophages, thus blocking the “don’t eat me” signal used by cancer cells to evade phagocytosis." (PMID 38673842, 2024). "In summary, our research underscores the dual-targeting proficiency of the small-molecule compound SMC18 against both the CD47/SIRPα and PD-1/PD-L1 pathways, bridging innate and adaptive immunity and thus providing a promising candidate for cancer immunotherapy." (PMID 38462636, 2024). "Cancer cells express CD47 to disrupt macrophage phagocytosis." (PMID 38405432, 2024).
cancer (continued). "Moreover, the expression of CD47 in adjacent tissues was observed to be higher than in cancer tissues, as evidenced in KICH and LUSC." (PMID 38720108, 2024). "Additionally, utilizing WB-PCR, it can be shown that CD47 wild-type cancer cells express a higher amount of T cell depletion factors compared to CD47 knockout cancer cells." (PMID 38720108, 2024). "In this regard, CD47 has been considered a target protein for cancer therapies." (PMID 39795582, 2024). "Interestingly, there was a direct correlation between EGFR activating mutations and elevated levels of CD47 and MHC I molecules on cancer cells." (PMID 38690738, 2024). "MYC is one of the most commonly activated oncogenes mediating cancer initiation and progression, and it regulates the expression of two immune checkpoints, CD47 and PD-L1, by directly binding to their promoters, leading to the identification of MYC as a target for immunotherapy resistance." (PMID 39199429, 2024). "Otherwise, tacking a step back to its primary high‐affinity ligand TSP1, that, like CD47, is upregulated in inflammation, transplantation, metabolic conditions, cancer and other diseases, could be an answer." (PMID 38362603, 2024). "Therefore, the expression status of CD47 needs to be researched in various malignant tumors in relation to treatment." (PMID 39795582, 2024). "Early studies have found that CD47 inhibits phagocytosis of tumor cells in cancer." (PMID 39165926, 2024). "The targeting capability of CD47 could be an immunotherapy strategy for the treatment of human cancers." (PMID 38832992, 2024). "ZEB1 and CD47 were colocalized within hypoxic cancer cell islets." (PMID 38183060, 2024). "Moreover, various approaches, such as monoclonal antibodies that block CD47-SIRPα interaction, appear to have promising and innovative potential in cancer immunotherapy." (PMID 39682556, 2024). "Additionally, we conducted an analysis of the expression profile and co-expression patterns of the T-cell depletion gene set CD47 across pan-cancer cohorts." (PMID 38720108, 2024). "CD47 and PD-L1 are widely studied immune checkpoint molecules that play a decisive role in the formation and maintenance of an inhibitory immune microenvironment in cancers." (PMID 39135122, 2024). "The research endeavors to explore the implications of CD47 in cancer immunotherapy effectiveness." (PMID 38720108, 2024). "Furthermore, evidence indicates that CD47, which is involved in the inhibition of efferocytosis, is overexpressed not only in cancer cells but also in atherosclerotic lesions." (PMID 39201377, 2024). "In conclusion, CD47 molecule might be a powerful prognostic and predictive factor in various cancers, although its potential in STS remains to be clarified." (PMID 38493445, 2024). "Whereas the binding of Gensci059 to CD47 depends on the level of CD47 N-terminal pyroglutamate cyclization, the high level of pyroglutamate cyclization in cancer cells may enhance their binding to Gensci059." (PMID 38429732, 2024). "Besides evading adaptive immunity, cancer cells can escape innate immune cells such as macrophages or dendritic cells (DCs) via CD47." (PMID 38414061, 2024). "We looked into CD47's carcinogenic potential using the XENA-TCGA GTEx pan-cancer database." (PMID 38720108, 2024). "This is the first report of a novel approach to target cancer cells with CD47-CAR-T cells." (PMID 38832992, 2024). "CD47 is highly expressed on cancer cells to evade phagocytosis by macrophages." (PMID 39702544, 2024). "Therefore, a series of inhibitors specifically developed to inhibit the CD47-SIRPα cancer signaling pathway have been created." (PMID 39795582, 2024). "Targeting CD47/SIRPα axis has emerged as a promising strategy in cancer immunotherapy." (PMID 38429732, 2024). "Treatment with an anti-CD47 antibody caused the formation of patches or foci of cancer cells that remained but also was not able to fully eliminate all cancer cells from the well." (PMID 38483480, 2024).